ST8SIA4 (ST8 alpha-N-acetyl-neuraminide alpha-2,8-sialyltransferase 4)
Description:
Catalyzes the transfer of a sialic acid from a CMP-linked sialic acid donor onto a terminal alpha-2,3-, alpha-2,6-, or alpha-2,8-linked sialic acid of an N-linked glycan protein acceptor through alpha-2,8-linkages. Therefore, participates in polysialic acid synthesis on various sialylated N-acetyllactosaminyl oligosaccharides, including NCAM1 N-glycans, FETUB N-glycans and AHSG. It is noteworthy that alpha-2,3-linked sialic acid is apparently a better acceptor than alpha-2,6-linked sialic acid.
Synonyms: SIAT8-D; ST8SiaIV; PST; PST1; SIAT8D; ST8SIA-IV
Tractability: Antibody: UniProt places it where antibodies can reach, with high confidence; UniProt predicts a signal peptide or a membrane-spanning region; its Gene Ontology location is reachable by antibodies, with medium confidence. PROTAC: ubiquitination databases record sites on it.
Gene: Protein-coding gene on chromosome 5 (100,806,933 to 100,903,285, reverse strand). Ensembl gene ENSG00000113532.
Subcellular location: Golgi apparatus membrane; Secreted
Subcellular location (Human Protein Atlas): Golgi apparatus; Predicted to be secreted
Pathways (Reactome):
Developmental Biology: NCAM1 interactions
Metabolism of proteins: Sialic acid metabolism
Gene Ontology:
Molecular function: alpha-N-acetylneuraminate alpha-2,8-sialyltransferase activity; sialyltransferase activity; sialic acid binding
Biological process: ganglioside biosynthetic process; glycoprotein biosynthetic process; N-glycan processing; oligosaccharide metabolic process; sialylation; nervous system development; protein modification process
Cellular component: extracellular region; Golgi apparatus; Golgi membrane
Genetic constraint (gnomAD): Loss-of-function variants: 15 observed, 33.81 expected, observed/expected ratio (o/e) 0.44, 90% interval 0.3 to 0.68. The upper end of that interval is the gene's LOEUF score, 0.68, which puts it in group 2 of 6, group 1 being the genes least tolerant of losing a copy. Missense variants: 321 observed, 452.22 expected, observed/expected ratio (o/e) 0.71, 90% interval 0.65 to 0.78. Synonymous variants: 171 observed, 161 expected, observed/expected ratio (o/e) 1.06, 90% interval 0.94 to 1.21.
Homologues: Orthologues: chimpanzee ST8SIA4 (100% identical), macaque ST8SIA4 (99% identical), dog ST8SIA4 (99% identical), rabbit ST8SIA4 (98% identical), mouse St8sia4 (98% identical), rat St8sia4 (98% identical), guinea pig ST8SIA4 (96% identical), tropical clawed frog st8sia4 (88% identical), pig ST8SIA4 (84% identical), zebrafish st8sia4 (69% identical). Paralogues in human: ST8SIA2 (59% identical), ST8SIA3 (35% identical), ST8SIA5 (29% identical), ST8SIA1 (26% identical), ST8SIA6 (25% identical).
Diseases named in the same sentence as ST8SIA4 in open-access papers:
ST8SIA4 is named in the same sentence as 25 diseases in open-access papers, as found by Europe PMC text mining. Sharing a sentence is not in itself a finding about the gene and the disease. The quoted sentences say what the papers report.
breast carcinoma (6 papers, 2016 to 2024). "Expression of ST8SIA4 in the MDA-MB-231 breast cancer line is associated with breast cancer metastasis." (PMID 39628991, 2024). "We described here a novel mechanism for the changes of breast cancer-associated N-glycan and sialylation and the suppression of ST8SIA4 by miR-26a/26b in breast cancer progression." (PMID 28032858, 2016). "Of these, three genes have higher expression in the tumor tissues including ST6GALNAC5 (2.31-folds), ST8SIA3 (1.78-folds) and ST8SIA4 (2.47-folds), suggesting that breast cancer expressed high levels of α2,6- and α2,8-linked sialylation." (PMID 28032858, 2016). "Overexpression of ST6GALNAC1 in the MDA-MB-231 breast cancer line has also been shown to promote the invasion and migration of breast cancer cells via the EMT pathway while higher levels of ST8SIA4 promote tumorigenicity in the same cancer cell line." (PMID 39628991, 2024). "Mass spectrometry analysis for N-glycan profiling in breast cancer tissues and cell lines identified ST8SIA4 as one of the most differentially expressed genes in MDA-MB-231 breast cancer cells compared to non-tumor MCF-10A cells." (PMID 33921986, 2021). "ST8SIA4 is significantly up-regulated in breast cancers and its up-regulation is highly correlated with cancer malignancy." (PMID 30517191, 2018). "Among these, the expression of ST6GALNAC5, ST8SIA3 and ST8SIA4 was significantly upregulated in breast cancer tissues compared with adjacent tissues, and ST8SIA2 and ST8SIA6 were upregulated in the adjacent tissues." (PMID 28032858, 2016). "To determine the clinical significance of ST8SIA4, we examined its expression pattern in tumor samples collected from breast cancer patients." (PMID 28032858, 2016). "To determine the impact of the miRNA-mediated downregulation of ST8SIA4 on breast tumor development, we assessed cell proliferation and invasion in breast cancer cell lines transfected with either control or miR-26a/26b mimics." (PMID 28032858, 2016). "In conclusion, by analyzing the sialylated N-glycans and expressional patterns of ST genes in breast cancer patients and in cell lines, ST8SIA4 regulation elucidated the unusual properties of breast cancer biological behavior." (PMID 28032858, 2016). "Clearly, further investigation was needed to elucidate the mechanistic roles of ST8SIA4 in breast cancer malignancy." (PMID 28032858, 2016). "Further data analysis revealed the inversely related expression of ST8SIA4 and miR-26a/26b in breast cancer cells, tumor tissues and corresponding adjacent tissues." (PMID 28032858, 2016). "Overall, our results demonstrated that ST8SIA4 indeed mediated tumor cell metastasis by modifying the sialylation profile in breast cancer cells." (PMID 28032858, 2016). "The ST8SIA4 mRNA expression appeared to be inversely correlated with the levels of miR-26a/26b (P<0.05), which was consistent with breast cancer cell lines." (PMID 28032858, 2016). "It has been reported that ST8SIA4 is closely related to metastasis in breast cancer." (PMID 33520692, 2020). "Indeed, increased expression of ST8SIA4 in human leukemia and decreased expression of B4GALT2 in breast cancer cells has been associated with multidrug resistance." (PMID 30651077, 2019). "We further investigated whether ST8SIA4 expression is regulated by endogenous miR-26a and miR-26b in breast cancer cell lines." (PMID 28032858, 2016). "We then examined whether the decrease in ST8SIA4 level is necessary for inhibition of breast cancer progression, and MDA-MB-231 cells were subjected to ST8SIA4 knockdown." (PMID 28032858, 2016). "In addition, we showed that miR-26a/26b was downregulated in breast cancer patients and invasive cells, and correlated with ST8SIA4 expression." (PMID 28032858, 2016).
breast carcinoma (continued). "In addition, the data revealed that expressional levels of ST3GAL6 (12.34-folds) and ST8SIA4 (5.71-folds) were upregulated in the highly metastatic breast cancer cell line MDA-MB-231 compared with the slightly metastatic breast cancer cell line MCF-7." (PMID 28032858, 2016). "The forced expression of miR-26a/26b was able to induce a decrease of ST8SIA4 level and also to affect breast cancer cells progression, while altered expression of ST8SIA4 in breast cancer cells modulated progression upon transfection with miR-26a/26b mimics or inhibiter." (PMID 28032858, 2016). "In particular, we showed here that ST8SIA4 was specifically upregulated in breast cancer tissues and MDA-MB-231 cells, and thus we speculated that ST8SIA4 was a key factor in promoting malignant progression of breast cancer." (PMID 28032858, 2016). "Interestingly, we also found that ST8SIA4 was one of the most notable genes that show higher expression patterns in breast cancer tissues." (PMID 28032858, 2016). "Moreover, miR-26a/26b reconstitution contributed to improving the capability of breast cancer cell progression by regulating ST8SIA4." (PMID 28032858, 2016). "In this regard, it would be conceivable that altered expression of miR-26a/26b targeting ST8SIA4 could downregulate ST8SIA4 levels to promote breast cancer progression, whereas ST8SIA4-mutant genetic background favored the miR-26a/26b-mediated cancer progression effect." (PMID 28032858, 2016). "Taken together, these results indicate that changes in the glycosylation patterns and sialylation levels may be useful markers of the progression of breast cancer, as well as miR-26a/26b may be widely involved in the regulation of sialylation machinery by targeting ST8SIA4." (PMID 28032858, 2016). "Ma and colleagues demonstrated that miR-26a and miR-26b negatively regulate ST8SIA4 via directly targeting the 3′-UTR of ST8SIA4 to inhibit migration and invasion in vitro of aggressive breast cancer cells." (PMID 33921986, 2021). "In comparison with MCF-10A cells, the aggressive breast cancer cell line MDA-MB-231 showed an increased number of differentially expressed genes including ST6GALNAC5 (7.33-folds), ST8SIA4 (14.81-folds) and ST8SIA5 (3.11-folds)." (PMID 28032858, 2016). "Our findings here that silencing of ST8SIA4 significantly inhibited MDA-MB-231 cell proliferation and invasion both in vitro and in vivo indicated an important role of ST8SIA4 in the stimulation of breast cancer cell progression." (PMID 28032858, 2016).
chronic myelocytic leukemia (4 papers, 2016 to 2025). "MiR-181c sensitizes chronic myelocytic leukemia (CML) to Adriamycin by targeting ST8SIA4 expression." (PMID 39820173, 2025). "Furthermore, increased level of ST8SIA4 was found, consistent with our previous finding in chronic myelocytic leukemia." (PMID 31096997, 2019).
follicular thyroid carcinoma (4 papers, 2017 to 2025). "In follicular thyroid carcinoma, miR-146a promotes cell migration and invasion by downregulating ST8SIA4 mRNA and affecting the PI3K-AKT-mTOR axis." (PMID 40277937, 2025). "Another report showed that ST8SIA4 can be inhibited by miR-146a and miR-146b in follicular thyroid carcinoma cells." (PMID 33921986, 2021).
schizophrenia (3 papers, 2013 to 2023). A major psychotic disorder characterized by abnormalities in the perception or expression of reality. "As NCAM is not the only substrate for ST8SIA2 and the underlying biosynthetic mechanisms of polySia by ST8SIA2 and ST8SIA4 are not well understood, it is important to focus on the contribution of glycoepitopes, such as polySia, to schizophrenia." (PMID 23675315, 2013). "In addition, several characteristic properties, such as brain structure, neural plasticity, and various morphological, cognitive, and emotional deficits related to schizophrenia have been observed in ST8SIA2- or ST8SIA4-SKO mice." (PMID 23675315, 2013). "At least seven genes putatively mapped by our significant non-reference TEs have been already associated with schizophrenia: LRRC4C, LRRC7, ST8SIA4, MGAM, ADAMTS1, MIR548AJ2 and SCN5A, which is also linked to the Brugada syndrome." (PMID 37244930, 2023).
glioma (2 papers, 2019 to 2023). A benign or malignant brain and spinal cord tumor that arises from glial cells (astrocytes, oligodendrocytes, ependymal cells). "LN229 cells expressed only ST8SIA4, and the glioma cell line U343 expressed none." (PMID 38067186, 2023).
leukemia (2 papers, 2016 to 2019). A malignant (clonal) hematologic disorder, involving hematopoietic stem cells and characterized by the presence of primitive or atypical myeloid or lymphoid cells in the bone marrow and the blood. "ST8SIA4 has been reported to enhance the chemoresistance in leukemia by phosphorylating and activating of Akt at Ser473 and Thr308 specifically and increasing the activity of PI3K/AKT signaling pathway." (PMID 27527856, 2016). "Increased expression of ST8SIA4 has been reported in diverse carcinomas and highly correlates with leukemia multidrug resistance (MDR)." (PMID 27527856, 2016).
pancreatic cancer (2 papers, 2016). "A sialyltransferase (ST8SIA4) has been shown to promote metastatic dissemination in pancreatic cancer by interfering with E-cadherin dependent cell adhesion." (PMID 26847345, 2016). "siRNA knockdown of N-CAM and ST8SIA4 abolished pancreatic cancer cell aggregation and migration." (PMID 28035996, 2016).
ankylosing spondylitis (1 paper, 2024). An autoimmune chronic inflammatory disorder characterized by inflammation in the vertebral joints of the spine and sacroiliac joints. "Ultimately, ST8SIA4 was confirmed as the most likely optimal diagnostic biomarker for AS combine with ankylosing spondylitis." (PMID 39131703, 2024). "Overall, our findings spotlight ST8SIA4 as a critical diagnostic gene and the lysosomal pathway as a common pathway in AS and ankylosing spondylitis, aiming to foster novel diagnostic and therapeutic approaches for these conditions." (PMID 39131703, 2024). "Our research further delved into the association between the ST8SIA4 gene and the immune system's cellular composition by evaluating the prevalence of 22 distinct immune cell types within samples from AS and ankylosing spondylitis." (PMID 39131703, 2024). "This study investigates the role of ST8SIA4 as a common diagnostic gene and the involvement of the lysosomal pathway in both AS and ankylosing spondylitis." (PMID 39131703, 2024). "This study identifies ST8SIA4 as a key diagnostic marker in the progression of AS and ankylosing spondylitis, noting a significant increase in its expression in affected patients." (PMID 39131703, 2024). "In this study, we employed bioinformatics techniques and machine learning algorithms to identify ST8SIA4 as a shared diagnostic gene for AS and ankylosing spondylitis." (PMID 39131703, 2024). "The potential of ST8SIA4 as a diagnostic biomarker for AS and ankylosing spondylitis was further validated." (PMID 39131703, 2024). "This investigation supports the potential of ST8SIA4 as a diagnostic biomarker and aids in exploring the common mechanisms associated with AS and ankylosing spondylitis." (PMID 39131703, 2024). "Subsequent verification across four datasets showed that ST8SIA4 expression levels were consistently higher in the AS or ankylosing spondylitis groups compared to healthy controls." (PMID 39131703, 2024).
breast tumor (1 paper, 2016). "Immunohistochemistry (IHC) staining showed that ST8SIA4 expression was significantly upregulated in breast tumor tissues as compared with adjacent tissues." (PMID 28032858, 2016).
cholangiocarcinoma (1 paper, 2020). A carcinoma that arises from the intrahepatic biliary tree (intrahepatic cholangiocarcinoma) or from the junction, or adjacent to the junction, of the right and left hepatic ducts (hilar cholangiocarcinoma). "The association between ST8SIA4 expression and the clinicopathological features of cholangiocarcinoma was assessed in 98 patient samples." (PMID 33520692, 2020). "miR-144-5p and miR-451a overexpression inhibited proliferation, invasion and migration of cholangiocarcinoma cells by down-regulating ST8SIA4." (PMID 33520692, 2020). "We also demonstrated that miR-144-5p and miR-451a inhibited the progression of cholangiocarcinoma through targeting ST8SIA4." (PMID 33520692, 2020). "Nevertheless, the mechanisms by which ST8SIA4 promoted the proliferation, migration and invasion capacities of cholangiocarcinoma cells remain to be elucidated." (PMID 33520692, 2020). "ST8SIA4 reversed the miR-144-5p- and miR-451a- induced the growth defect of cholangiocarcinoma cells, and presented a correlation with the expression of these two microRNAs in patient samples." (PMID 33520692, 2020). "Overexpression of ST8SIA4 promoted the proliferation, invasion and migration of cholangiocarcinoma cells, and the changes were reversed by upregulating the expression of miR-144-5p and miR-451a." (PMID 33520692, 2020). "Correlations between ST8SIA4 expression levels and clinicopathological features in cholangiocarcinoma." (PMID 33520692, 2020). "The increased expression of miR-144-5p and miR-451a prevented proliferation, migration and invasion of cholangiocarcinoma cells through suppressing the expression of ST8SIA4." (PMID 33520692, 2020). "Our findings indicated that miR-144-5p and miR-451a displayed a tumor suppressor role through decreasing the expression of ST8SIA4 in cholangiocarcinoma." (PMID 33520692, 2020). "We next investigated the function of ST8SIA4 in cholangiocarcinoma." (PMID 33520692, 2020). "Moreover, ST8SIA4 rescued the miR-144-5p- and miR-451a-induced the growth defect of cholangiocarcinoma cells." (PMID 33520692, 2020). "Moreover, the transcriptional and translational levels of ST8SIA4 were increased to a certain extent in cholangiocarcinoma tissues compared with the adjacent normal bile duct tissues." (PMID 33520692, 2020). "The newly discovered miR-144-5p/miR-451a-ST8SIA4 signaling axis might be of importance to understand the progression and metastasis of cholangiocarcinoma cells." (PMID 33520692, 2020). "Cholangiocarcinoma cells were transfected with miR-144-5p, miR-451a mimics or inhibitors together with ST8SIA4 expression plasmids or siRNA-3# to further assess whether miR-144-5p and miR-451a can restrain the cholangiocarcinoma cell proliferation, invasion, and migration by regulating ST8SIA4." (PMID 33520692, 2020).
colorectal cancer (1 paper, 2022). A primary or metastatic malignant neoplasm that affects the colon or rectum. "For example, in colorectal cancer, an increase in the expression of ST8SIA4, ST3GAL6, ST6GALNAC5 is associated with an increase in regulatory T cells and pro-tumoral M2 macrophages." (PMID 36009354, 2022).
glioblastoma (1 paper, 2016). The most malignant astrocytic tumor (WHO grade IV). "A missense mutation of ST8SIA4 (R168S) was reported as one of the driver mutations in glioblastoma." (PMID 28035996, 2016).
lymph node metastasis (1 paper, 2020). "ST8SIA4 expression levels were significantly correlated with HBsAg and the presence of lymph node metastasis." (PMID 33520692, 2020).
thyroid carcinoma (1 paper, 2017). "miR-146a and miR-146b were previously shown to be upregulated in thyroid carcinoma, and bioinformatics analyses indicated that miR-146a and miR-146b inhibit ST8SIA4." (PMID 28427206, 2017).
cancer (12 papers, 2013 to 2025). A tumor composed of atypical neoplastic, often pleomorphic cells that invade other tissues. "ST8SIA4 is involved in sialylation of proteins associated with cancer progression." (PMID 30517191, 2018). "Intriguingly, Kaplan Meier analysis revealed poorer survival for patients with higher levels of either ST6GAL1, ST3GAL2 and ST8SIA4, similarly to what observed in other cancer models." (PMID 41226744, 2025). "In ESCC, increased sialylation mediated by ST8SIA4 can enhance the metastatic potential of cancer cells by promoting cell adhesion, migration, and invasion through interactions with sialoglycan-binding lectins, such as Siglecs and selectins." (PMID 41286778, 2025). "We investigated the role of ST8SIA2 and ST8SIA4 related to the production of dPSA on the surface of cancer cells." (PMID 34544457, 2021). "ST8SIA4 is expressed in fetal and adult brain, spleen, thymus, and peripheral blood leukocytes and in cancer." (PMID 34544457, 2021). "The protein product of ST8SIA4 is known to be involved in the polysialylation of neural cell adhesion molecule (NCAM), which has been linked to cancer development and dissemination." (PMID 23305139, 2013). "ST8SIA4 has been identified as a potential glycan cancer marker in much of the literature." (PMID 33520692, 2020). "Herein we demonstrated that miR-181c targets the 3′ UTR of the sialylation related gene ST8SIA4, suggesting the enzyme may play a role in cancer chemoresistance." (PMID 27527856, 2016).